KPNA2 (karyopherin subunit alpha 2)
Diseases named in the same sentence as KPNA2 in open-access papers (continued):
Sharing a sentence is not in itself a finding about the gene and the disease.
glioma (12 papers, 2018 to 2025). A benign or malignant brain and spinal cord tumor that arises from glial cells (astrocytes, oligodendrocytes, ependymal cells). "The downregulation of miR-1297 and upregulation of KPNA2 in glioma implied a regulatory association between them." (PMID 35912242, 2022). "In glioma, knockdown of KPNA2 decreased the levels of MYC and this was linked to decreased proliferation and invasion." (PMID 32512858, 2020). "On the other hand, correlation between the expressions of KPNA2 and ki-67 were shown, further demonstrating that upregulation of KPNA2 was associated with poor prognosis of the glioma patients." (PMID 30115078, 2018). "The results indicated that overexpression of KPNA2 was indeed an independent risk factor of gliomas in the patients." (PMID 30115078, 2018). "For example, the action mechanism of KPNA2, a prognostic marker, in tumorigenesis and the progression of glioma occurs in part by regulating metabolism." (PMID 40507925, 2025). "After processing raw data from TCGA and CGGA, we separated the glioma data into low and high groups according to KPNA2 expression." (PMID 37423952, 2023). "In conclusion, ZNF143 mediates the Hippo/YAP signalling pathway and inhibits the growth and migration of glioma cells by regulating KPNA2." (PMID 37423952, 2023). "In the present study, proliferation and migration were significantly decreased, and apoptosis was greatly facilitated in glioma cells by KPNA2 knockdown." (PMID 37423952, 2023). "The present study aims to investigate the role of ZNF143 (zinc finger protein 143, the transcription factor of KPNA2) in regulating the effects of KPNA2 on glioma and to explore novel therapeutic targets for glioma." (PMID 37423952, 2023). "In conclusion, the present study revealed that KPNA2 regulates biological behaviours, such as the proliferation, migration, invasion and apoptosis of glioma cells, by regulating the Hippo signalling pathway." (PMID 37423952, 2023). "To explore the function of KPNA2 in the development of glioma, we used survival analysis by the Kaplan‒Meier method to assess the overall survival (OS) of patients with low and high KPNA2 expression in the TCGA and CGGA cohorts." (PMID 37423952, 2023). "Western blotting assays and RT‒PCR assays were utilized to determine the expression level of KPNA2 in glioma cells." (PMID 37423952, 2023). "Karyopherin alpha 2 (KPNA2, 58 kDa) is one of seven members of the karyopherin α-family; Dysregulation of KPNA2 had been reported serving as a potential biomarker in several malignancies, including breast cancer, gastric cancer, lung cancer, and glioma." (PMID 36199790, 2022). "IL-10 has been shown to enhance the expression of KPNA2, which affects cell growth and expression in cancer cells, including the human brain tumor, suggesting that IL-10 promotes glioma cell growth and invasion by regulating KPNA2." (PMID 36009467, 2022). "In the present study, we found that KPNA2 was highly expressed in the glioma compared to the normal brain tissues, and the level of KPNA2 was an independent predictor of prognosis in the glioma patients." (PMID 30115078, 2018). "Immunohistochemical (IHC) analysis was performed and the results showed that the expression of KPNA2 was increased with the grades of malignancy in gliomas." (PMID 30115078, 2018). "Considering the in vitro involvement of KPNA2 in glioma cell proliferation, survival and metabolism, we extended our study to determine the impact of KPNA2 depletion on tumorigenic capacity of glioma cells in vivo." (PMID 30115078, 2018). "On the contrary, level of glucose had a minor effect on the growth kinetics of the glioma cells when KPNA2 was depleted, suggesting that the cells with higher level of KPNA2 relied on glucose as their major energy source." (PMID 30115078, 2018).
glioma (continued). "In the present study, we found that KPNA2 was highly expressed in the glioma compared to the normal brain tissues." (PMID 30115078, 2018). "We observed that glycolytic metabolism such as activities of the key enzymes in glycolysis and lactic acid production was significant decreased in the KPNA2-knockdown glioma cell lines U87 and U251." (PMID 30115078, 2018). "In this study, we performed IHC analysis and confirmed that KPNA2 was indeed elevated in the glioma specimens compared to the normal brain tissues." (PMID 30115078, 2018). "Moreover, ZNF143 targeted the promoter region of KPNA2 and positively regulated the expression level of KPNA2, which formed a positive feedback loop to jointly regulate the malignant progression of glioma cells." (PMID 37423952, 2023). "Furthermore, we found that KPNA2 was significantly highly expressed in glioma in both the TCGA and CGGA databases." (PMID 37423952, 2023). "The results of the present study showed that KPNA2 was upregulated in glioma cells, indicating that KPNA2 might be involved in the pathogenesis of glioma." (PMID 37423952, 2023). "In vitro, it has been demonstrated that IL-10 upregulates KPNA2 (a gene coding for nuclear import of proteins); at the same time, knockdown experiments showed that glioma cell growth and invasion were significantly reduced, suggesting IL-10 as a potential target for glioma patients’ treatment." (PMID 33804731, 2021). "Additionally we observed that KPNA2 appeared to be predominantly situated in the nuclei of glioma cells." (PMID 30115078, 2018). "Growth kinetics of the cells was additionally suppressed when KPNA2 was knockdown, evidently indicating that KPNA2 might have multiple effects on the metabolic reprogramming of gliomas." (PMID 30115078, 2018). "Level of KPNA2 was an independent predictor of prognosis in the glioma patients." (PMID 30115078, 2018). "In consideration of KPNA2 role in c-myc transactivation, we applied ChIP assay to the glioma cells." (PMID 30115078, 2018). "High level of KPNA2 predicted poor prognosis for the glioma patients." (PMID 30115078, 2018). "To test this hypothesis, we first examined the effects of KPNA2 exerting to E2F1 in the glioma cells." (PMID 30115078, 2018). "Compared to NHA cells, KPNA2 was significantly upregulated in U373 cells (*p < 0.05 vs. NHA), which was consistent with the results observed in glioma tissues in the TCGA dataset." (PMID 37423952, 2023). "However, the exact mechanism of KPNA2 in gliomas remains unclear." (PMID 37423952, 2023). "Downregulation of ZNF143 and KPNA2 can activate the Hippo signalling pathway and reduce YAP/TAZ expression in human glioma cells, thus inducing apoptosis of human glioma cells and weakening their proliferation, migration and invasion." (PMID 37423952, 2023). "In view of this, we focused our attention on investigating the interactions between KPNA2, c-myc and E2F1 in the glycolytic transformation of gliomas." (PMID 30115078, 2018). "In view of this, we hypothesized that in glioma cells, E2F1 may be involved in the transcriptional regulation of c-myc by KPNA2." (PMID 30115078, 2018).
colorectal cancer (11 papers, 2006 to 2023). A primary or metastatic malignant neoplasm that affects the colon or rectum. "In colorectal cancer cells, upregulated KPNA2 was demonstrated to be associated with immunogenic cell death." (PMID 33193737, 2020). "Studies have revealed that elevated expression of KPNA2 can be associated to colorectal cancer progression, can be used as a novel diagnostic and prognostic marker as well as a therapeutic target for colorectal cancer." (PMID 31581454, 2019). "Furthermore, the subgroup analysis revealed that KPNA2 overexpression was associated with poor OS in East-Asian patients and European patients, as well as patients with gastric and colorectal cancer." (PMID 27974678, 2017). "Here, we showed that KPNA2 was significantly increased by radiation in the human colorectal cancer cell lines HT29 and HCT116." (PMID 31212646, 2019). "The results of KPNA2 silencing in MDA-MB231 cells were consistent with those in colorectal cancer cells, indicating that KPNA2 is a target to circumvent radioresistance." (PMID 31212646, 2019). "We detected a marked induction of KPNA2 expression upon IR exposure in colorectal cancer HT29 and HCT116 cells in a time- and dose-dependent manner." (PMID 31212646, 2019). "In a previous study, we identified karyopherin-α2 (KPNA2, also called importin-α1) as a protein upregulated in human colorectal cancer HT29 cells exposed to single or fractionated IR." (PMID 31212646, 2019). "Finally, when data was stratified according to cancer type, the results showed the prognostic value of KPNA2 overexpression for OS was significant in gastric cancer and colorectal cancer." (PMID 27974678, 2017). "KPNA2 might play an important role in colorectal carcinogenesis and functions as a novel prognostic indicator and a potential therapeutic target for colorectal cancer." (PMID 26626145, 2015). "We identified three proteins of tumorigenesis: CAV1, KPNA2, and PRMT5 being downregulated by GS treatment in colorectal cancer HCT 116 cells." (PMID 31581454, 2019). "KPNA2 promotes tumor progression by activating the AKT pathway in ovarian and colorectal cancer." (PMID 34903711, 2021). "Among the up-regulated genes in colorectal cancer, we found 14 genes involved in signal transduction (TDGF1 and ENC1), transcription (SOX9, MYC, and HGFR/MET), nuclear transport (NUP62, NUPL1, NUP155, KPNA2, RANBP5, CSE1L/CAS, NTF2, and RANBP1) and cellular transport (SLCO4A1)." (PMID 16919171, 2006).
gastric cancer (11 papers, 2016 to 2024). A primary or metastatic malignant neoplasm involving the stomach. "And the protein level of KPNA2 was highly expressed in gastric cancer cells and gastric cancer tissues." (PMID 39060340, 2024). "Microarray and immunohistochemistry assays have shown that KPNA2 expression is higher in several cancer specimens, such as breast, colon, lung, oral, pancreatic, and gastric cancers, compared with adjacent normal tissue." (PMID 31212646, 2019). "In gastric cancer, miR-26b-5p inhibited metastasis by regulating the KPNA2/c-jun pathway." (PMID 32512858, 2020). "Moreover, we simultaneously down-regulated KPNA2 (sh-1 or sh-2) and up-regulated WDR62 in gastric cancer cells, and found that overexpression of WDR62 reversed the KPNA2 knockdown-induced inhibition of proliferation, migration and invasion." (PMID 39060340, 2024). "In this study, we explored the latent function of KPNA2, which is an essential member of the RBP family, in the regulation of alternative splicing (AS) in gastric cancer (GC)." (PMID 39060340, 2024).
colon cancer (10 papers, 2013 to 2024). "Previous reports indicate that KPNA2 contributed to the inflammatory processes in tumors and was also involved in the carcinogenesis of various malignancies such as melanoma, HCC, colon cancer, and so forth, and high expression of KPNA2 was associated with poor outcomes of patients." (PMID 35140750, 2022). "CENP-A recruits histone acetyltransferase, GCN-5, to KPNA2’s promoter regions to induce transcriptional activation, thereby augmenting colon cancer development." (PMID 39273649, 2024). "CENP-A also strengthens glycolysis in colon cancer by acting as an upstream transcription activator of an oncogene, KPNA2 (Karyopherin α2 subunit), that is known to be involved in metabolic reprogramming in cancer." (PMID 39273649, 2024). "CENPA acts as an upstream transcriptional activator of the karyopherin α2 subunit gene (KPNA2), indirectly promoting tumor cell growth and glycolysis in patients with colon cancer." (PMID 35938165, 2022). "We examined the KPNA2 expression with immunohistrochemistry using our in-house tumor microarray which contains 55 primary colon cancer specimens, 15 lymph node metastases and 50 corresponding adjacent normal tissues from patients of various disease stages." (PMID 23536776, 2013). "We found a drastic increase in KPNA2 expression in primary and lymph node metastatic colon tumors compared to adjacent normal tissues." (PMID 23536776, 2013). "Similar to colon cancer, oral and laryngeal squamous cell carcinomas displayed elevated levels of KPNA2 compared to independent mouth and larynx normal tissues." (PMID 23536776, 2013). "And CENPA can recruit histone acetyltransferase (HAT) general control of amino acid synthesis (GCN)-5 to the karyopherin α2 subunit gene (KPNA2) promoter region to epigenetically activate its transcriptional activity, resulting in glycolysis and malignant growth in colon cancer (CC) cells." (PMID 37457582, 2023).
prostate carcinoma (10 papers, 2012 to 2024). A carcinoma that arises from epithelial cells of the prostate gland. "KPNA2 is a member of the karyopherin family of nuclear export proteins and has been shown to have prognostic value in multiple cancer types including breast and prostate cancer." (PMID 39041188, 2024). "Importantly, the expression amounts of KPNA2 was comparable between HNSCC and prostate cancers, whereas KPNA4 is most abundant in HNSCC." (PMID 31822798, 2020). "Neither NBN gain nor NBN mRNA expression (or expression of its partner, KPNA2) was prognostic in the surgery cohort; consistent with previous publications on Nibrin expression in surgically treated prostate cancer patients." (PMID 25415046, 2014). "In earlier studies, using the same large prostate cancer cohort we had described other very strong and often independent prognostic features such as for example ß3-tubulin, CD57, DAXX, HOXB13, KPNA2, RBM3, mTOR, p62, and TYMS, that might also be worth testing in multiparametric prognostic kits." (PMID 28415558, 2017).
melanoma (9 papers, 2017 to 2024). A malignant, usually aggressive tumor composed of atypical, neoplastic melanocytes. "We aimed to elucidate the underlying mechanism of the CREB1/miR-495-3p/KPNA2 axis in melanoma progression." (PMID 36522613, 2022). "In melanoma, KPNA2 expression is associated with a worse prognosis, and its function in promoting proliferation, invasion and migration has been linked to NF‐κB/p65 signalling pathways." (PMID 36320118, 2022). "KPNA2, DTL, BACE2 and DTYMK cfRNA demonstrated high diagnostic accuracy between melanoma patients’ and healthy donors’ plasma (AUC > 86%, p < .0001)." (PMID 36320118, 2022). "Subsequently, KPNA2 expression was significantly decreased in melanoma tissues and cells, especially in A375 and B16 cells." (PMID 36522613, 2022). "In summary, our research illustrates that CREB1 regulates KPNA2 by inhibiting miR-495-3p transcription to regulate melanoma progression." (PMID 36522613, 2022). "Our findings highlight the specific molecular mechanism by which the CREB1/miR-495-3p/KPNA2 axis regulates melanoma progression." (PMID 36522613, 2022). "Our findings show that KPNA2 is highly expressed in melanoma tissues and cell lines and that CREB1 overexpression promotes KPNA2 expression." (PMID 36522613, 2022). "Four of those showed reliably quantifiable cfRNA copies in plasma samples and specific expression to melanoma (KPNA2, DTL, BACE2 and DTYMK)." (PMID 36320118, 2022). "Our study demonstrates for the first time that CREB1 participates in the regulation of melanoma progression through the miR-495-3p/KPNA2 axis." (PMID 36522613, 2022). "Our results indicate the molecular mechanism by which the CREB1/miR-495-3p/KPNA2 axis regulates melanoma progression." (PMID 36522613, 2022). "Our findings illustrate that CREB1 regulates KPNA2 by inhibiting miR-495-3p transcription to control melanoma progression." (PMID 36522613, 2022). "This study on the function of the CREB1/miR-495-3p/KPNA2 axis in the development and metastasis of melanoma provides new insight into the pathogenesis of melanoma and a promising method for the treatment of melanoma." (PMID 36522613, 2022). "Within the cytokine signaling pathway, GBP5 and KPNA2 have known roles in the immunomodulation and progression of melanoma, respectively." (PMID 35008167, 2021). "Moreover, functional experiments further showed that CREB1 regulates KPNA2 by inhibiting miR-495-3p transcription to enhance melanoma cell viability." (PMID 36522613, 2022). "Next, plasma cfRNA samples from melanoma patients (N = 18) versus control plasma of healthy donors (N = 18) were used to determine gene expression levels of six gene candidates (KPNA2, DTL, BACE2, DTYMK, E2F3 and SLC25A13) that showed excellent diagnostic accuracy (AUC >90.0%) in tissue." (PMID 36320118, 2022). "In summary, we hypothesized that the transcription factor CREB1 increases KPNA2 expression by inhibiting miR-495-3p transcription, which in turn promotes the development and metastasis of melanoma cells." (PMID 36522613, 2022). "We mainly clarify the role of the CREB1/miR-495-3p/KPNA2 axis in melanoma." (PMID 36522613, 2022). "CREB1 regulates KPNA2 by inhibiting miR-495-3p transcription to control melanoma progression." (PMID 36522613, 2022). "Through the re‐analysis of single‐cell RNA‐Seq (sc‐RNA‐Seq) data derived from 31 melanoma patients, we found that KPNA2, DTL, BACE2 and DTYMK are not only expressed by melanoma cells, but also by non‐malignant cells such as endothelial cells, cancer‐associated fibroblasts (CAFs), and immune cells." (PMID 36320118, 2022). "Our results indicate that miR-495-3p targets KPNA2 in melanoma." (PMID 36522613, 2022). "We also analysed cfRNA copies of KPNA2, DTL, BACE2 and DTYMK across different mutational genotypes of melanoma tissue (N = 33 BRAF/NRAS wild‐type, of those N = 4 positive for TERTprom; N = 41 BRAFV600 mutant and N = 25 NRASQ61 mutant melanomas)." (PMID 36320118, 2022).
melanoma (continued). "Therefore, we conclude that CREB1 regulated KPNA2 by inhibiting miR-495-3p transcription to enhance melanoma cell viability." (PMID 36522613, 2022). "However, whether miR-495-3p is involved in melanoma progression by targeting KPNA2 remains unclear." (PMID 36522613, 2022). "In summary, we have identified KPNA2, DTL, BACE2 and DTYMK cfRNAs as potential pan‐tumour liquid biopsy markers for prognostic and therapy monitoring in melanoma independent of the mutational genotype." (PMID 36320118, 2022). "Moreover, miR-495-3p targeted KPNA2, and CREB1 regulated KPNA2 by inhibiting miR-495-3p transcription to enhance melanoma cell viability." (PMID 36522613, 2022). "Receiver operating characteristic (ROC) curves showed an area under the curve (AUC) >90.0% for KPNA2, DTL, BACE2, DTYMK, E2F3 and SLC25A13, >80.0% for CCNA2, FOXM1, KIF4A, SLC45A2, COPS8, SLC45A13 and 70.0% for CDC25A and LINC00520; all significantly discriminating melanoma from benign nevi." (PMID 36320118, 2022). "We identified KPNA2, DTL, BACE2 and DTYMK messenger RNA (mRNA) upregulated in melanoma versus nevi tissues by unsupervised data mining (N = 175 melanoma, N = 20 normal skin, N = 6 benign nevi) and experimentally confirmed differential mRNA expression in vitro (N = 18 melanoma, N = 8 benign nevi)." (PMID 36320118, 2022).